NLRP3 (NLR family pyrin domain containing 3)
Diseases named in the same sentence as NLRP3 in open-access papers (continued):
Sharing a sentence is not in itself a finding about the gene and the disease.
Obesity (continued). "First, they observed that Nlrp3−/− mutant mice presented a protective phenotype against obesity-induced neuroinflammation." (PMID 34070553, 2021). "Reciprocal transplants of WT or Nlrp3–/– BM into irradiated ob/ob recipients also suggest a role for the inflammasome in the obesity-induced BM phenotype." (PMID 33554957, 2021). "Based on our results, we suggest that the NLRP3 inflammasome participates in the pathogenesis of obesity-induced IR in skeletal muscle tissue." (PMID 34638553, 2021). "This classical NLRP3 inflammasome activation occurs in invading ATM’s resulting from an obesity-mediated alteration in adipose tissue microenvironment." (PMID 33435142, 2021). "The review includes a broadened approach to the role of obesity-related diseases (obesity, low-grade chronic inflammation, type 2 diabetes, insulin resistance, and enhanced NLRP3 activity) in AD." (PMID 34070553, 2021). "This section summarizes the consequences of NLRP3 inflammasome activation in obesity-induced inflammation and insulin resistance." (PMID 33435142, 2021). "Research relating to the modulation of the NLRP3 inflammasome by diet and fatty acid-induced obesity will open new avenues for nutrient-sensitive metabolic inflammation." (PMID 33435142, 2021). "Collectively, these data suggest that NLRP3 inhibitors are potential targets in obesity-induced inflammation and insulin resistance, NAFLD and NASH." (PMID 34513923, 2021). "For example, activation of Toll-like receptors (TLRs) or NLRP3 inflammasome is known to instigate the development of obesity and type 2 diabetes." (PMID 34832960, 2021). "Other labs have also investigated the involvement of IL-1β and the NLRP3 inflammasome in the propagation of myelopoiesis in obesity." (PMID 33554957, 2021). "The present results of our analysis in the liver indicate a site-dependent NLRP3 inflammasome regulation throughout obesity, since overexpression of NLRP3, CASP1 (p20), and IL-18 (p18) took place only at 16 week of DIO." (PMID 34805147, 2021). "Findings are suggesting that activation of the inflammasome complex (particularly NLRP3) by DAMPs has a crucial role in obesity-induced inflammation, insulin resistance, and T2DM." (PMID 34070553, 2021). "The role of NLRP3 inflammasome activation in the exacerbation of obesity-mediated metabolic disorders and many other diseases opens new avenues for treating or relieving complications associated with these disorders." (PMID 33435142, 2021). "We propose that in skeletal muscle, obesity activates the NLRP3 inflammasome, which in turn cleaves and activates IL-1β." (PMID 34638553, 2021). "Multiple human and animal studies have indicated that NLRP3 is activated in adipose tissues with aging and obesity, and its inactivation significantly alleviates metabolic disorders." (PMID 32545355, 2020). "The focus of this review is on our recent elucidation of NLRP3’s mechanism of activation and its participation in the pathogenesis of obesity/T2D and AD." (PMID 32012695, 2020). "Surprisingly, the myeloid cell-specific deletion of Sptlc-2 did not prevent HFD-induced adipose tissue inflammation and insulin resistance, suggesting its dispensable role in NLRP3 inflammasome activation in obesity." (PMID 32545355, 2020). "The role of NLRP3 inflammasomes in the pathogenesis of obesity has been supported by data showing that Nlrp3–/– and Asc–/– knockout mice are protected from obesity and IR induced by a high-fat diet." (PMID 33519369, 2020). "Activation of NLRP3 inflammasome is also involved in the development of obesity-related kidney disease." (PMID 32175320, 2020). "NLRP3-produced IL-1β and IL-8 have been demonstrated to be involved in inflammation induced by obesity, T2D, and decreased insulin sensitivity." (PMID 32604771, 2020). "Overactivation of the NLRP3 inflammasome contributes to accelerated pathogenesis and complications of obesity-related conditions such as type 2 diabetes (T2D), atherosclerosis, and gout." (PMID 32209983, 2020).
Obesity (continued). "Obesity and metabolic syndrome induce NLRP3 inflammatory activation, which weakens phospholipid degradation, leading to kidney damage." (PMID 33050202, 2020). "Equally, inhibition or genetic deletion of key components the NLRP3 inflammasome reduced systemic inflammation in models of diet‐induced obesity and protected again the development of peripheral insulin resistance in mice." (PMID 32608058, 2020). "Obesity activates inflammasome NLRP3 and increases IL-1β through activation of caspase 1 and causes insulin resistance and reduction in fat oxidation." (PMID 33113859, 2020). "HFD induces obesity in Nlrp3 global knockout mice but prevents the development of adipose tissue inflammation and insulin resistance." (PMID 33379163, 2020). "Two well-characterized conditions, in which the aberrant activity of the NLRP3 inflammasome contributes to and exacerbates pathology, leading to inflammaging, are obesity and diabetes." (PMID 32751530, 2020). "Other studies also point to the participation of NLRP3 in obesity because of its overexpression in AT." (PMID 32012695, 2020). "The NLRP3 inflammasome impairs insulin sensitivity in dietary-induced obesity via the disruption of phosphatidylinositol 3-kinase-protein kinase B (PI3K-Akt) signaling, a major pathway orchestrating the metabolic effects of insulin in peripheral tissue." (PMID 32545355, 2020). "Human studies indicated that NLRP3 activity in adipose tissues positively correlates with obesity and its metabolic complications, and treatment with the IL-1β antibody improves glycaemia control in type 2 diabetic patients." (PMID 32545355, 2020). "A previous study noted that the NOD-like receptor pyrin containing 3 (NLRP3) inflammasome is a culprit of obesity and IR and that obese Nlrp3-/- knockout (KO) mice are more insulin sensitive than obese wild-type mice." (PMID 32580621, 2020). "In this context, insulin resistance (present in most populations with obesity) depends on NLRP3 (NOD-, LRR-, and pyrin domain-containing protein 3) inflammasome activation affecting B and T cells response." (PMID 33299523, 2020). "Paradoxically, NLRP3 inflammasome was revealed to aggravate adipose tissue fibrosis during the progression of obesity, which limits healthy adipocyte expansion and elevates circulating levels of FFAs." (PMID 32545355, 2020). "Although the net effects of altered bile acid composition in NLRP3 deficient mice are at present not clear, our findings should warrant further studies on the interaction between bile acids and NLRP3 inflammasome in obesity and related disorders." (PMID 33273482, 2020). "The NLRP3 inflammasome is involved in the pathogenesis of obesity-related inflammatory diseases, including metabolic syndrome, type 2 diabetes, and cardiovascular diseases." (PMID 32161574, 2020). "Studies suggest a significant role of NLRP3 inflammasome in the initiation and progression of metaflammation (i.e., metabolically-induced inflammation) and related diseases, such as obesity, T2DM, NAFLD, and atherosclerosis." (PMID 33273482, 2020). "In response to calorie restriction and exercise, gene expressions of IL-1β and NLRP3 are reduced in the subcutaneous fat of patients with obesity and type 2 diabetes, accompanied with improvement in insulin sensitivity." (PMID 32545355, 2020). "Genetic ablation of NLRP3 prevented obesity-induced inflammasome and caspase 1 activation in the liver as well as improved insulin sensitivity." (PMID 32992548, 2020). "For instance, NLRP3 inflammasome is upregulated in differentiating adipocytes and elimination of NLRP3 inflammasome protects against obesity-induced pancreatic damage and metabolic dysfunction." (PMID 32155890, 2020). "Apart from its deleterious effects on the peripheral tissues, activation of the NLRP3 inflammasome in vWAT has been recently report to impair the central nervous system in cases of obesity." (PMID 32545355, 2020).
Obesity (continued). "Inflammasome, NLRP3, is a well-characterized complex, which gets activated in obesity-related type 2 diabetes." (PMID 32282828, 2020). "In animal models of HFD-induced obesity, NLRP3, ASC and caspase-1 inhibition also ameliorated the disease." (PMID 32545788, 2020). "Here, we explore in how inflammaging and metaflammation affect type-2 diabetes or obesity, as well as the fundamental role of the NLRP3 inflammasome in these conditions." (PMID 32604771, 2020). "During ischemia and reperfusion, ethanol, obesity (saturated fatty acids), and ROS can induce NLRP3 inflammasome activation." (PMID 32148650, 2020). "As obesity continues to spread worldwide, we also evaluated the NLRP3 response in experimental cholangitis after high-fat diet exposure." (PMID 32716024, 2020). "The reduction of such markers is also in accordance with a recent study in which ω-3 fatty acids suppresses NLRP3 inflammasome signaling in adipose tissue of individuals with obesity." (PMID 32906847, 2020). "It has been conclusively demonstrated that obesity triggers NLRP3 activation and that secreted IL-1β that impairs insulin signaling, which contributes to IR in mice." (PMID 33519369, 2020). "Bruton's tyrosine kinase (BTK) is highly expressed in monocytes and macrophages and regulates NF‐κB and NLRP3 inflammasome activity; both propagate metabolic inflammation in diet‐induced obesity." (PMID 32608058, 2020). "The NLRP3-inflammasome is one of the most established multi-protein complexes known for instigating obesity-induced inflammation." (PMID 32492941, 2020). "Meanwhile, some compounds specifically inhibit activation of NLRP3 inflammasome and cytokine production in adipocytes although NLRP3 inflammasomes were activated in obesity-induced inflammation." (PMID 33126679, 2020). "Several molecules have been identified as DAMPs involved in NLRP3 activation in HFD-induced obesity." (PMID 31582899, 2019). "The primary role played by NLRP3 inflammasome is also supported by evidence that genetic ablation of NLRP3–/– prevents the obesity-induced inflammasome activation in AT and protects against HFD-induced IR." (PMID 32063863, 2019). "Hexokinase-1 mediated glycolysis regulates the NLR Family Pyrin Domain Containing 3 (NLRP3) inflammasome, a multiprotein complex implicated in obesity-related inflammation as well as several pulmonary diseases." (PMID 30990817, 2019). "Nlrp3 and ASC (Pycard) deficient mice were also protected against obesity-induced systemic metabolic dysregulation, as well as lipid accumulation and impaired insulin signaling in hepatic and cardiac tissues." (PMID 31379826, 2019). "A loss-of-function animal study showed that NLRP3-, ASC-, and caspase-1-deficient mice are protected from HFD-induced obesity and show improved glucose tolerance and insulin sensitivity." (PMID 31582899, 2019). "It has been reported that obesity can accelerate vascular endothelial dysfunction via the activation of NLRP3 inflammasome and mitochondrial dysfunction." (PMID 30941060, 2019). "In particular, several studies have shown that NLRP3-/-, caspase-1-/-, and ASC-/- mice were less susceptible to the development of obesity induced by high-fat diet (HFD)." (PMID 31200447, 2019). "Compelling evidence shows that NLRP3 (the most studied member of the NLR family) activation by DAMPs (generated by nutrient excess in obesity) plays a key role behind the chronic inflammation characteristic of obesity and IR." (PMID 32063863, 2019). "The decline in NLRP3 inflammasome-mediated IL-1β activation also improves obesity-induced insulin resistance." (PMID 31174550, 2019). "Accumulating evidence highlights a central role for the NLRP3 inflammasome in obesity-induced insulin resistance." (PMID 31835423, 2019). "Exposure to a HFD for 52 weeks induced profound obesity as compared to mice fed a control diet in all three genotypes (i.e., WT, Nlrp3−/−, and Asc−/− [Pycard−/−] mice)." (PMID 31379826, 2019).
Obesity (continued). "Compelling evidence suggests a significant role of NLRP3 inflammasome in the initiation and progression of metaflammation (i.e., metabolically-induced inflammation) and related diseases, such as obesity, T2DM, NAFLD, and atherosclerosis." (PMID 31379826, 2019). "Here, we evaluated the role of inflammasome NLRP3 and caspases 1/11 in the establishment of obesity and hepatic steatosis in diet-induced obese mice, correlating them with the global lipid profile of the liver and gut microbiota diversity." (PMID 31998283, 2019). "NLRP3 inflammasome signaling is regarded as a potential culprit in obesity-mediated insulin resistance and T2DM." (PMID 31174550, 2019). "By using Nlrp3−/−, Nlrc4−/−, Casp1/11−/−, and WT obesity-prone C57BL/6 mice, another study concluded that the NLRC4 inflammasome, associated often with obesity, has a more important role in BC progression than the NLRP3 inflammasome." (PMID 31661891, 2019). "Two recent papers reported that phytochemicals acting on NLRP3 activation alleviated obesity-induced renal damage and diabetic nephropathy." (PMID 31200447, 2019). "Obesity-induced inflammation, triggered by lipid-mediated activation of the Nlrp3 inflammasome, results in glucose metabolism alterations and type 2 diabetes." (PMID 31554824, 2019). "They showed that the NLRP3 inflammasome, in addition to its role in the innate immune response, contributes to obesity-induced insulin resistance." (PMID 31174550, 2019). "SFAs, such as palmitate and ceramides, can stimulate NLRP3 inflammasome activation to induce inflammation and obesity-mediated T2DM." (PMID 31582899, 2019). "While obese WT mice showed a marked reduction in Akt phosphorylation upon insulin treatment in both cardiac and hepatic tissue, Nlrp3−/− mice were protected against this obesity-induced effect." (PMID 31379826, 2019). "Evidence showed that obesity triggered NLRP3 activation, and that the secreted IL-1β impaired insulin signaling which promoted insulin resistance in mice." (PMID 29686666, 2018). "In summary, it is likely that the two inflammasome sensors, NLRP1 and NLRP3, exert opposite effects in obesity; NLRP1 cleavage of IL-18 acts to limit metabolic dysfunction, while NLRP3 activation of IL-1β is detrimental and promotes glucose intolerance." (PMID 29515457, 2018). "In NLRP3 knockout mice, elimination of NLRP3 ameliorated obesity-induced inflammation and insulin resistance, and caspase-1 knockout mice also improved glucose tolerance and insulin sensitivity than wild-type mice after feeding a high-fat diet." (PMID 29497383, 2018). "Obesity-related inflammation is partly mediated by the NLRP3 inflammasome, and NLRP3 activation exacerbates obesity-linked diseases." (PMID 30574122, 2018). "The NLRP3 inflammasome has been correlated with obesity-induced insulin resistance and pancreas beta cell failure, which is the cause of type 2 diabetes." (PMID 29853850, 2018). "It has been shown that NLRP3 inflammasome can sense ceramides generated from saturated fatty acids under condition of lipid surplus and contribute to obesity-induced inflammation and insulin resistance." (PMID 29538286, 2018). "Further experiments, for example, laminar shear‐stress to mimic the exercise effect at the cellular level, are needed to confirm the effect of exercise on NLRP3 inflammasome pathways in vascular function in obesity." (PMID 29932503, 2018). "It had been reported that activation of the NLRP3 inflammasome correlates with obesity and insulin resistance (IR)." (PMID 29675053, 2018). "In another study, GDF15 transgenic mice were resistant to diet- and genetically induced obesity and exhibited improved insulin sensitivity due to a reduction in NLRP3 inflammasome activity in adipose tissue, in the context of obesity and insulin resistance." (PMID 29674655, 2018).
Obesity (continued). "Obesity itself also promote the assembly of the NLRP3 inflammasome in ATMs, inducing macrophage-mediated T cell activation that, through the release of INF-γ, mediates insulin resistance." (PMID 30619282, 2018). "Regarding the suppressive effect of voluntary running exercise on NLRP3 inflammasome activation in obesity, we propose several possible inhibitory pathways." (PMID 29932503, 2018). "Obesity-related molecules such as ROS, ceramides, palmitate and elevated circulating glucose activate the NLRP3 (NLR family, pyrin domain containing 3) inflammasome through phosphorylation of NFκB p65, leading to immune cell infiltration." (PMID 29497784, 2018). "Nevertheless, further studies are needed to determine if vitamin D supplementation can improve outcomes in obesity patients with asthma and the exact role of vitamin D in regulating NLRP3 inflammasome activity." (PMID 29160418, 2017). "Obesity-induced danger signals have been reported to activate the NLRP3 inflammasome and induce the production of IL-1β in adipose tissue in T2D patients and in mice fed a high-fat diet." (PMID 28115020, 2017). "The NLRP3 inflammasome assembles in response to many stimuli including endogenous obesity-induced metabolites, such as the accumulation of ROS." (PMID 29186929, 2017). "During the progression of obesity, the NLRP3 inflammasome regulates the innate immune response within AT." (PMID 29186929, 2017). "Unfortunately though, to our knowledge, this is the only in vivo investigation into the ability of dietary LC n-3 PUFA to modulate the NLRP3 inflammasome in obesity." (PMID 29186929, 2017). "Nlrp3 is thought to be part of the mechanism by which obesity leads to other pathologies such as T2DM and GDM." (PMID 28212289, 2017). "After fifteen weeks, all obesogenic diets led to increased weight in the vehicle group, however the pharmacological inhibition of NLRP3- protected these animals from obesity, similar to the genetic NLRP3 deletion." (PMID 29245937, 2017). "It appears that NLRP3 inflammasome is involved in the interaction of vitamin D3 in obesity with asthma." (PMID 29160418, 2017). "The expression levels of IL-1β mRNA and NLRP3 mRNA in lung tissue of the obesity and asthma groups were increased." (PMID 29160418, 2017). "Activation of the NLRP-3 inflammasome in course of diet-induced obesity in mice led to an increase in IL-18 secretion and was shown to affect insulin signaling." (PMID 26788518, 2016). "Future research using FACS analysis is needed to examine the differential inflammatory effects of obesity and Nlrp3 ablation in AT immune cells (i.e., macrophages, T-cells) vs. adipocytes." (PMID 27583382, 2016). "NLRP3 has been recently shown to play a key role in the pathogenesis of insulin resistance and obesity, and is regulated by compounds such as ceramide, which induce IL-1β processing via caspase-1 activation." (PMID 27812198, 2016). "More research is needed to examine vascular effects of Nlrp3 signaling in the setting of obesity and metabolic disease." (PMID 27583382, 2016). "The NLRP3 inflammasome can also sense metabolic “danger signals” originating from Western diet and obesity such as glucose, cholesterol, free fatty acids, uric acid, and reactive oxygen species." (PMID 27583382, 2016). "Recent reports suggest that activated ceramide induces caspase-1 activation, IL-1β production in an Nlrp3 inflammasome dependent mechanism in obesity or acute lung injury." (PMID 26980705, 2016). "To further explore the mechanism of obesity-induced Nlrp3 inflammasome activation in HFD fed mice, we determined the NADPH oxidase derived O2•− production in Asm+/+ and Asm−/− mice." (PMID 26980705, 2016). "Using podocin as a podocyte marker, our confocal observations demonstrated that obesity-induced inflammasome formation in glomeruli was mostly located in podocytes as demonstrated by the colocalization of Nlrp3 with podocin." (PMID 26980705, 2016).